FOXP3 (forkhead box P3)
Diseases named in the same sentence as FOXP3 in open-access papers (continued):
Sharing a sentence is not in itself a finding about the gene and the disease.
Chronic colitis (14 papers, 2011 to 2024). A chronic inflammatory disease of the large intestine (colon, cecum and rectum). "Deficiency of TGF-β1 or Foxp3, factors necessary for Treg cell differentiation, induces chronic colitis." (PMID 31534467, 2019). "BBR activates the AMP-activated protein kinase pathway and increases forkhead box P3 (FOXP3) levels, thereby promoting Treg cell differentiation in chronic colitis mice." (PMID 39472803, 2024). "Of note, it is known that Akkermansia (A.)muciniphila has a protective effect against inflammation because A. muciniphila ameliorates chronic colitis of mice through the cross-talk of microbe-derived SCFAs and Foxp3+ Treg." (PMID 36891315, 2023). "In contrast, the absence of miR-155 overexpression in the sigmoid colon of PSC-UC patients activated the Il-6/S1PR1 signalling pathway and imbalanced the IL17/FOXP3 ratio, which reinforces chronic colitis." (PMID 35563301, 2022). "In conclusion, TOE is effective in preventing chronic colitis through the upregulation of FOXP3+ Treg cells and its secreted anti-inflammatory cytokine, IL-10." (PMID 33092149, 2020). "In our study, HQT treatment was associated with a significant increase in the number of CD4+CD25+ Foxp3+ Treg cells and in the expression level of Foxp3 in the colon of mice with DSS-induced chronic colitis." (PMID 27982094, 2016). "Based on these ex vivo results, we next used immunohistochemistry to examine the ratio of FoxP3 positive cells to total CD3 positive cells in mice affected with chronic colitis." (PMID 21806815, 2011). "Our work indicates that the increased FoxP3+ cell population in the ILK-ko mice is associated with a concomitant reduction in the IL-17+ cell population, in response to induction of chronic colitis." (PMID 21806815, 2011). "Thus, we demonstrated A. muciniphila strain ATCC to ameliorate chronic colitis of mice through the cross-talk of microbe-derived SCFAs and Foxp3+ Treg cells." (PMID 31334133, 2019). "In contrast, antigen (flagellin)-specific IFN-gamma+Foxp3+ Treg cells tested for suppression capacity in the same model of chronic colitis were found to maintain their regulatory function without reporting on Treg cell marker expression." (PMID 30936873, 2019). "Moreover, compared to the chronic colitis mice treated with PBS, those mice treated with IL-33 showed a marked increase in the expression of Foxp3 mRNAs." (PMID 30539029, 2018). "However, in the chronic colitis model, increased expression of both CCR4 and Foxp3 was detected in CD200tg mice, with an increased ratio of Foxp3+:CD3+ cells enumerated in the same CD200tg mice both in colonic tissue sections and by FACS staining of isolated mesenteric lymph node cells." (PMID 26841120, 2016).
co-infection (14 papers, 2009 to 2024). "Ascaris single and coinfection were associated with a rise of CD4-CD8α+FoxP3+ Treg in the lymph nodes draining the small intestine and liver." (PMID 39140728, 2024). "One limitation of the study is that we only evaluated the association between monocyte subsets and Foxp3+ Tregs during T. pallidum/HIV-1 co-infection by phenotyping." (PMID 31024549, 2019). "Thus, HCV/HIV coinfection was associated with an enrichment of FoxP3+ subsets within the CD4 T cell compartment and relative preservation of FoxP3+ Tregs in circulating lymphocytes." (PMID 25071758, 2014). "In our study, we observed elevated ability of TGF-β secretion in Foxp3+CD4+ T cells in TB and HIV infection, and HIV/TB co-infection further enhanced the production of TGF-β in Foxp3+CD4+ T cells when compared with TB." (PMID 37483385, 2023). "Polyfunctional ex vivo restimulation followed by ICS revealed that on day 6 and 9 after IAV (co)infection, the frequencies of Foxp3+ Tregs producing IL-10 were significantly increased in the lungs of (co)infected compared with Mtb-alone-infected mice." (PMID 30998505, 2019). "Relevant to this perhaps is the increase in FoxP3 cells detected in the T zone after co-infection compared to STm alone." (PMID 25474738, 2014). "However, few data are available concerning the changes in Foxp3+Helios+ Tregs in T. pallidum/HIV-1 co-infections." (PMID 31024549, 2019). "This study, to the best of our knowledge, represents the first report reflecting the delicate link between NF-κB, TNF-α, IL-6, FoxP3 splice variants and HO-1 genes and their relationship with HIV disease progression and explains how Mtb co-infection modulates these links to the advantage of HIV." (PMID 25198707, 2014). "The Foxp3+Helios+CD45RA+ and Foxp3+CD25+CD45RA+ Treg populations expanded during syphilis and during T. pallidum/HIV-1 co-infection." (PMID 31024549, 2019). "The frequencies of Foxp3+Helios+CD45RA+ and Foxp3+CD25+CD45RA+ Tregs were lower during T. pallidum/HIV-1 co-infection than during infection with HIV-1 alone." (PMID 31024549, 2019). "We also noted increased proportions of CD4+CD25+FoxP3+ regulatory T cells in patients with S. stercoralis and HTLV-1 co-infection compared to either normal controls or patients infected with either HTLV-1 or S. stercoralis only." (PMID 19513105, 2009). "Our data does not support a role for suppressive effects of FoxP3+ Tregs in mediating this effect since the expansion of Tregs is comparable during co-infection compared to a single Plasmodium infection." (PMID 25996913, 2015). "With the onset of PTB co-infection in the dampened immune environment of HIV-1 infected individuals, we observed further significant increase in Foxp3 expression in CD4 T-cells of co-infected individuals in comparison to individuals infected only with HIV-1 but similar CD4 count (<250 cells/μl)." (PMID 25198707, 2014). "In addition, we show that co-infection significantly reduced pulmonary IFN-γ, TGF-β and Foxp3 gene expression, relative to BCG-only infected mice." (PMID 24433309, 2014). "Indeed, the proportion of CD4+ cells that were CD25+FoxP3+ was dramatically increased in patients with S. stercoralis and HTLV-1 co-infection." (PMID 19513105, 2009). "The intermediate levels of FoxP3 T cells observed during co-infection may paradoxically have a negative effect on Nb clearance through enhancing Th1 inflammation and thus restricting the limited Th2 response induced from functioning." (PMID 25474738, 2014). "There was a significantly higher frequency of CD25+FoxP3+ CD4 T-cells in PTB infected individuals with (mean±SEM: 8.57±1.07, p = 0.0012) and without (mean±SEM: 6.09±0.39, p = 0.035) HIV-1 co-infection when compared to healthy controls (mean±SEM: 5.04±0.33)." (PMID 25198707, 2014).
Hypertension (14 papers, 2013 to 2025). The presence of chronic increased pressure in the systemic arterial system. "Research has shown that reducing the methylation of Foxp3 can restore Treg function, potentially alleviating hypertension-associated immune inflammation." (PMID 40079010, 2025). "Studies have shown that modulating the methylation state of the Foxp3 gene can enhance Tregs’ anti-inflammatory activity, potentially alleviating hypertension-related immune inflammation." (PMID 40079010, 2025). "The real relationship between the excessive expression of OX40 on CD4+CD25+FoxP3+ cells and the severity of changes in the maternal body in the course of pregnancy-induced hypertension certainly requires further research." (PMID 37887878, 2023). "Among our patients, the population of CD4+CD25+Foxp3+ cells was slightly lower in the group of women with hypertension." (PMID 37887878, 2023). "In conclusion, this study uncovers a crucial role of Nox2 in CD4+CD25+FoxP3+ Tregs in regulating Ang II–induced hypertension and cardiac remodeling." (PMID 29688896, 2018). "The major novel finding of this study is that the expression of Nox2 in CD4+CD25+FoxP3+ Tregs plays a vital role in their function to orchestrate Ang II–induced hypertension and cardiac remodeling." (PMID 29688896, 2018). "More recently, it has been found that Tregs (CD4+CD25+FoxP3+) can act to limit Ang II–induced inflammation and damage in the vasculature and heart, thereby reducing the extent of hypertension and cardiac remodeling." (PMID 29688896, 2018). "Moreover, DEL-1–Fc injections during hypertension resulted in higher numbers of CD25+FoxP3+ Tregs and increased IL-10 compared with injections of DEL-1–RGE–Fc." (PMID 35133978, 2022). "An animal model study showed that hypertension induced by angiotensin II (Ang II) in a mouse model leads to an increase in the expression of complement component 3a receptor (C3aR) and complement component 5a receptor (C5aR) in forkhead box P3 (Foxp3) + regulatory cells (Tregs)." (PMID 38791032, 2024). "Patients suffering from hypertension showed higher percentages of Tregs expressing PD-1 on the surface than the HC group: Foxp3+Helios-CD279+ Tregs, Foxp3+Helios+CD279+ Tregs and Foxp3-Helios+CD279+ Tregs." (PMID 40243452, 2025). "The aim of this study was to assess the population of circulating CD4+CD25+FoxP3+ cells and its differentiation in terms of CD134 expression in two forms of hypertension: isolated hypertension developing after the 20th week of pregnancy and pre-eclampsia." (PMID 37887878, 2023). "As a result, this suppresses the expression of the master transcription factor forkhead box P3 (FoxP3) in regulatory T (Treg) cells and activates T helper 17 (Th17) cells to secrete IL23, further contributing to development of hypertension." (PMID 38045685, 2023). "The aim of this study was to assess the population of circulating CD4+CD25+FoxP3+ cells and its differentiation in terms of OX40 expression in two forms of hypertension: isolated hypertension developing after the 20th week of pregnancy and pre-eclampsia." (PMID 37887878, 2023). "The proinflammatory profile during ANGII-induced hypertension is accompanied by a destabilized and reduced antiinflammatory CD4+FoxP3+ Treg response along with a decrease in IL-10 production." (PMID 35133978, 2022). "There are 2 major proinflammatory actions driving hypertensive cardiovascular remodeling and hypertension: leukocyte recruitment into cardiovascular tissues followed by T cell/IL-17–driven inflammation and, simultaneously, a destabilized/reduced antiinflammatory CD4+FoxP3+ Treg/IL-10 response." (PMID 35133978, 2022). "We also observed greater FoxP3+ T regulatory cell infiltration into the aorta of hypertensive mice, which may suggest non-selective recruitment of T cells during hypertension." (PMID 25501574, 2014).
Hypertension (continued). "Despite the absence of an increase in the proportion of CD4+FoxP3+ (Treg) cells in the recipient WKY, the increased proportion of CD4+IL-17A+ (Th17) cells did not affect the onset of hypertension." (PMID 33688497, 2021).
type 2 diabetes (14 papers, 2011 to 2025). "In the nucleus, enolase binds to regulatory regions of FOXP3 and directly affects the expression of the splicing variant Foxp3-E2, which was corroborated in peripheral blood samples from patients with type 2 diabetes and relapsing-remitting multiple sclerosis." (PMID 33114536, 2020). "This study aimed to investigate the association between FOXP3 polymorphisms and the susceptibility to T2DM and type 2 diabetes nephropathy (T2DN) within the Han Chinese populations." (PMID 36717877, 2023). "In patients with Type 2 diabetes, black tea consumption was associated with increased regulatory T cells (CD3+ CD4+ CD25+ FOXP3) and immunosuppressive CD3+ CD4+ IL-10+ cells, alongside reduced proinflammatory CD3+ CD4+ IL-17+ cells and Th1-associated CD3+ CD4+ IFN-γ+ cells." (PMID 40008375, 2025). "Therefore, Cp also simultaneously stimulated the growth of Akkermansia spp., which could alleviate symptoms of type 2 diabetes by induction of Tregs (Foxp3+ T cells)." (PMID 30211217, 2018). "In conclusion, traditional Chinese medicine GAG, which effectively treats type 2 diabetes in clinic, can also alleviate autoimmune T1DM in NOD mice by upregulating both CD4+FoxP3+ and CD8+CD122+PD1+ Tregs." (PMID 28947964, 2017). "The aim of this study was to examine the fluctuations in CD4+ T cells, CD8+ T cells, and natural CD4+CD25+FoxP3+T-regulatory (Treg) cells following an oral glucose tolerance test (OGTT) in participants with and those without type 2 diabetes (T2DM)." (PMID 29615971, 2018).
chronic hepatitis C (13 papers, 2009 to 2025). "Therefore, if the *C variant maintains FOXP3 gene expression, this variant may participate in the immunopathogenesis of chronic hepatitis C infection, likely through activation of intrahepatic Tregs." (PMID 30233595, 2018). "CD4+CD25+FOXP3+ Tregs accounted for 14.24±1.33% of CD4+ T cells in the peripheral blood obtained from patients with chronic hepatitis C, which was higher than that of the healthy control subjects (5.62±1.21%; P<0.001, Table I)." (PMID 24944616, 2014). "CD4+CD25+FOXP3+ Tregs accounted for 14.24±1.33% of the CD4+ T cells in the peripheral blood of patients with chronic hepatitis C, which was higher than that of the healthy control subjects (5.62±1.21%; P<0.001)." (PMID 24944616, 2014). "The present study demonstrated that the percentage of CD4+CD25+FOXP3+ Tregs in CD4+ T cells obtained from the peripheral blood was greater in patients with chronic hepatitis C than in the healthy control subjects, indicating that Tregs are overexpressed in HCV infected patients." (PMID 24944616, 2014). "We found reduced frequencies of peripheral Foxp3+CD25+CD127lowCD4+ Tregs in patients with PSC as compared to healthy controls, whereas frequencies of Tregs were markedly enhanced in patients with chronic hepatitis C." (PMID 38607233, 2024). "LTA inhibits the proliferation of CD4(+) T-cells in a FoxP3(+) Treg-dependent manner in patients with chronic hepatitis C, suggesting that LTA acts on FoxP3." (PMID 33671013, 2021). "The percentage of CD4+CD25+FOXP3+ Tregs was greater in patients with chronic hepatitis C than in the healthy control subjects and CD4+CD25+FOXP3+ Tregs were able to inhibit the response of CD8+ T lymphocytes to various virus antigens, thus, promoting chronic HCV infection." (PMID 24944616, 2014). "Patients with chronic hepatitis C may produce certain factors that stimulate the hyperplasia and maturity of CD4+CD25+FOXP3+ Tregs." (PMID 24944616, 2014).
colorectal tumors (13 papers, 2016 to 2025). "In our study, we found that KIF18A inhibition by AM-1882 enhanced infiltrating of CD45+ leukocytes, CD3+ T cells, CD3+CD8+ Cytotoxic T (Cyto T) cells, and decreased infiltrating of CD25+FoxP3+ regulator T (Treg) cells in CIN+ colorectal tumors." (PMID 40175357, 2025). "Collective literature indicated a poor prognosis for cancers with an abundance of intratumoral FOXP3+ Treg cells, whereas a minority of studies showed an advantageous survival in colorectal tumors with FOXP3+ T‐cell infiltrates." (PMID 34159752, 2021). "This supports the recent observations that IL2RB expression is correlated with mRNA expression of FOXP3 in cytolytic (CYT-high) colorectal tumors." (PMID 33928242, 2021). "We found that CD4+CD25+FoxP3+ Tregs accumulate in colorectal tumors at significantly higher levels, compared to periphery and adjacent colon normal tissues." (PMID 31921188, 2019). "We find it plausible that colorectal tumor–specific Treg cells in advanced disease are detrimental to patients, and high preexisting Foxp3+ Treg cell infiltration is a bystander effect of a larger antitumor immune response." (PMID 28880972, 2017). "A role of FoxP3-expressing Tregs has remained ambiguous in colorectal tumor progression, as some studies showed a protective role of FoxP3-expressing Tregs in CRC, while other studies have shown it to be associated with an adverse outcome of the patients." (PMID 28603527, 2017). "This was in agreement with a study that showed increased frequencies of FoxP3− Treg cells in colorectal tumors, which were even more suppressive than FoxP3+ Treg cells and produced IL-10 and TGF-β." (PMID 27014625, 2016). "Single cell suspensions obtained from both colorectal tumors and adjacent uninvolved tissue were stained for markers of Treg cells, including CD4, CD25, CD127, FOXP3, and CD39, and were analyzed by flow cytometry." (PMID 27014625, 2016).